MIR1264 (microRNA 1264)
Synonyms: hsa-mir-1264; MIRN1264
Gene: MicroRNA gene on chromosome X (114,652,655 to 114,652,723, forward strand). Ensembl gene ENSG00000276158.
Homologues: Orthologues: macaque MIR1264 (100% identical).